TIPE1 (TNF alpha induced protein 8 like 1)
Description:
Acts as a negative regulator of mTOR activity.
Synonyms: TNFAIP8L1; MGC17791
Tractability: PROTAC: ubiquitination databases record sites on it.
Gene: Protein-coding gene on chromosome 19 (4,639,511 to 4,655,568, forward strand). Ensembl gene ENSG00000185361.
Subcellular location: Cytoplasm
Pathways (Reactome):
Metabolism: PI Metabolism
Gene Ontology:
Molecular function: identical protein binding; protein binding
Biological process: negative regulation of TOR signaling; regulation of apoptotic process
Cellular component: cytoplasm
Genetic constraint (gnomAD): Loss-of-function variants: 1 observed, 0.27 expected, observed/expected ratio (o/e) 3.64. That is too few expected variants to judge how well the gene tolerates losing a copy. Missense variants: 225 observed, 223.45 expected, observed/expected ratio (o/e) 1.01, 90% interval 0.9 to 1.12. Synonymous variants: 127 observed, 105.73 expected, observed/expected ratio (o/e) 1.2, 90% interval 1.04 to 1.39.
Homologues: Orthologues: chimpanzee TNFAIP8L1 (100% identical), macaque TNFAIP8L1 (99% identical), dog TNFAIP8L1 (90% identical), pig TNFAIP8L1 (87% identical), mouse Tnfaip8l1 (82% identical), rat Tnfaip8l1 (78% identical), zebrafish tnfaip8l1 (68% identical), Drosophila melanogaster sigmar (34% identical). Paralogues in human: TIPE2 (57% identical), TNFAIP8 (56% identical), TIPE3 (55% identical).
Diseases named in the same sentence as TIPE1 in open-access papers:
TIPE1 is named in the same sentence as 41 diseases in open-access papers, as found by Europe PMC text mining. Sharing a sentence is not in itself a finding about the gene and the disease. The quoted sentences say what the papers report.
hepatocellular carcinoma (11 papers, 2015 to 2022). A malignant tumor that arises from hepatocytes. "To date, a great deal of evidence has shown that TIPE1 plays crucial roles in the carcinogenesis of many cancers, including hepatocellular carcinoma, gastric cancer, lung cancer, osteosarcoma, cervical cancer, colon cancer and breast cancer." (PMID 32588529, 2020). "A very recent study indicates that TIPE1 induces apoptosis by negatively regulating Rac1 activation in hepatocellular carcinoma cells." (PMID 28994231, 2018). "Our previous studies found that TIPE1 was downregulated in hepatocellular carcinoma which could induce caspase-mediated apoptosis and inhibit HCC cell growth both in vitro and in vivo." (PMID 34188681, 2021). "To date, several studies have shown that TIPE1 can inhibit the activation of Rac1, its downstream target p65, and the c-Jun N-terminal kinase pathway in hepatocellular carcinoma cells and decrease mTOR phosphorylation by stabilizing TSC2 protein in a Parkinson's disease model." (PMID 31179241, 2019). "Examples of these include Cu/Zn-superoxide dismutase (SOD1) mutant-induced motoneuronal cell death, Cisplatin-induced apoptosis in NIH3T3 cells, UV-induced apoptosis in COS-1 cells, TIPE1- induced apoptosis in hepatocellular carcinoma cells, and TNF-α-induced apoptosis in endothelial cells." (PMID 29321004, 2018). "Until now, only one study have shown that TIPE1 could induced hepatocellular carcinoma (HCC) cell apoptosis by targeting Rac1." (PMID 29108244, 2017). "Previous studies have shown that TIPE1 could induce apoptosis in hepatocellular carcinoma." (PMID 26207809, 2015). "TIPE1 can induce apoptosis in RAW264.7 and hepatocellular carcinoma cells by increasing the levels of Bcl‐2 family proteins or down‐regulating the Rac1 pathway." (PMID 32588529, 2020). "Previous study of TIPE1 function on hepatocellular carcinoma (HCC) cells demonstrated that TIPE1 could induce apoptosis of HCC cells by negatively regulate the expression of Rac1." (PMID 26207809, 2015). "Although previous studies have shown that TIPE1 could induce apoptosis in hepatocellular carcinoma (HCC) cells by regulating Rac1, little is known about its structure." (PMID 26207809, 2015).
cervical cancer (8 papers, 2019 to 2022). A primary or metastatic malignant neoplasm involving the cervix. "We observed the expression of TIPE1 in cisplatin-resistant cervical cancer cell lines is increased compared to their matched sensitive cell lines (Data not shown)." (PMID 33520705, 2020). "The results indicated that TIPE1 is responsible for the transition from chemosensitivity to chemoresistance, and that it can serve as a promising target in cervical cancer chemotherapy." (PMID 33520705, 2020). "TIPE1 inhibits tumour proliferation and metastasis in a variety of tumours but acts as an oncogene in cervical cancer." (PMID 32588529, 2020). "Given that TIPE1 has been substantiated as a positive inducer in cervical cancer chemoresistance, we further verified its role in chemoresistance in vivo." (PMID 33520705, 2020). "Similar to cervical cancer, our group also revealed that TIPE1 was upregulated in nasopharyngeal carcinoma, in which TIPE1 plays an important role in the induction of cell growth, proliferation and colony formation." (PMID 33520705, 2020). "Here, we revealed that TIPE1 inhibits chemoresistant cervical cancer cell apoptosis both in vivo and in vitro." (PMID 33520705, 2020). "Here, we revealed that TIPE1 inhibits cervical cancer cell apoptosis both in vivo and in vitro." (PMID 33520705, 2020). "Here, we showed that TIPE1 inhibits cervical cancer cell apoptosis both in vivo and in vitro." (PMID 33520705, 2020). "Consistent with the results of our previous research in cervical cancer, TIPE1 may serve as an oncogene in NPC." (PMID 32588529, 2020). "However, we recently demonstrated that TIPE1 significantly induces cell proliferation and tumor burden in cervical cancer." (PMID 33520705, 2020). "Moreover, TIPE2 can sensitize osteosarcoma cells to cis-platin by downregulating MDR1 transcription, while TIPE1 promotes cervical cancer progression." (PMID 31179241, 2019). "However, our recent research demonstrated that it serves as an oncogene in the pathogenesis of cervical cancer, indicating that the role of TIPE1 in carcinogenesis needs to be further evaluated." (PMID 31179241, 2019). "However, TIPE1 mRNA is upregulated in several cancer cell lines, and our previous study also showed that it promotes cervical cancer proliferation." (PMID 31179241, 2019).
cervical cancer (continued). "Additionally, it has been reported that TIPE1 mRNA levels are increased in certain human tumor cells, including cervical cancer cells and tongue cancer cells, indirectly demonstrating that TIPE1 might serve as an oncogene in some types of tumors." (PMID 36151091, 2022). "However, some researchers discovered that TIPE1 could promote cell proliferation of cervical cancer and nasopharyngeal carcinoma, suggesting that TIPE1 may have different effects in different types of tumors." (PMID 34188681, 2021). "However, our recent research demonstrated that TIPE1 could promote cervical cancer proliferation, and thus preserves it as a poor prognostic factor for patients with cervical cancer, indicating that its biological functions for tumorigenesis remain ambiguous." (PMID 31179241, 2019). "On the other hand, TIPE1 expression was elevated, and its expression was positively correlated to MKI67 expression in cervical cancer tissues." (PMID 36118167, 2022).
nasopharyngeal carcinoma (5 papers, 2020 to 2024). A carcinoma arising from the nasopharyngeal epithelium. "However, TIPE1 can be upregulated in nasopharyngeal carcinoma, suggesting a role in promoting the proliferation of nasopharyngeal carcinoma cells." (PMID 36118167, 2022). "Additionally, the overexpression of TIPE1 reduced the levels of pAMPK and LC3B, thereby inhibiting autophagy in nasopharyngeal carcinoma cells." (PMID 38216955, 2024). "The role of TIPE1 in nasopharyngeal carcinoma (NPC) remains unknown." (PMID 32588529, 2020).
Parkinson disease (5 papers, 2017 to 2022). A progressive degenerative disorder of the central nervous system characterized by loss of dopamine producing neurons in the substantia nigra and the presence of Lewy bodies in the substantia nigra and locus coeruleus. "Altered regulation of TIPE1 may contribute to deregulated autophagy seen in dopaminergic neurons under pathogenic oxidative stress, which is especially observed in post-mortem brains in Parkinson’s disease." (PMID 30274259, 2018). "For instance, TIPE and TIPE1 function as autophagy inhibitors and activators in experimental models of Parkinson’s disease." (PMID 30274259, 2018). "TIPE2 and TIPE1 have been found to exert their effect in Myasthenia Gravis and Parkinson’s disease, respectively, and thus can serve as important targets for therapies against these diseases." (PMID 30274259, 2018). "In a Parkinson’s disease model, TIPE1 binds to FBXW5, increasing autophagy through activation of TSC2." (PMID 29108244, 2017). "Moreover, TIPE1 decreases mTOR phosphorylation by stabilizing TSC2 protein in a Parkinson's disease model." (PMID 31179241, 2019). "Previous work has shown that TIPE1/Oxi-beta can competitively bind to FBXW5 with tuberous sclerosis complex 2 (TSC2), increasing the stability of TSC2 and promoting excessive autophagy in Parkinson’s disease." (PMID 36118167, 2022).
breast carcinoma (4 papers, 2019 to 2024). "Our results will provide supporting evidence to warrant further investigation of TIPE1 as a therapeutic target and a diagnostic biomarker in breast cancer." (PMID 31179241, 2019). "Patient's characteristics and association of TIPE1 levels with clinicopathological features in breast cancer population." (PMID 31179241, 2019). "This study also suggests that TIPE1 could serve as a potential therapeutic target and a diagnostic biomarker for breast cancer." (PMID 31179241, 2019). "We found higher TIPE1 expression in tumor tissues from patients with lymphoma compared with those with lymphadenitis, breast cancer, or bladder cancer." (PMID 36118167, 2022). "We also demonstrated for the first time that TIPE1 was markedly downregulated in human breast cancer tissues." (PMID 31179241, 2019). "Taken together, these results indicate that TIPE1 can significantly inhibit breast cancer cell growth in vitro." (PMID 31179241, 2019). "This phenomenon should urge us to further validate the relationship between TIPE1 and ER status in breast cancer in the future." (PMID 31179241, 2019). "We found that low TIPE1 expression was correlated with poor disease-free survival and overall survival in breast cancer patients [p < 0.0001, HR 95% CI = 0.72 (0.61–0.84); p = 0.015, HR 95% CI = 0.68 (0.49–0.93), respectively]." (PMID 31179241, 2019). "In this study, we show that TIPE1 is able to inhibit breast cancer cell growth both in vivo and in vitro." (PMID 31179241, 2019). "Further analysis indicated that the expression of TIPE1 was also negatively associated with Ki67 levels, further indicating that TIPE1 suppresses cell proliferation in breast cancer." (PMID 31179241, 2019). "First, we investigated that TIPE1 suppresses breast cancer cell proliferation both in vitro and in vivo." (PMID 31179241, 2019). "Here, we showed that TIPE1 significantly decreases breast cancer cell growth both in vivo and in vitro." (PMID 31179241, 2019). "In summary, we demonstrated that TIPE1 suppresses breast cancer proliferation by inhibiting ERK activation." (PMID 31179241, 2019). "A CCK-8 assay was then performed to investigate the role of TIPE1 in breast cancer cell growth in vitro." (PMID 31179241, 2019). "To further confirm the roles of TIPE1 in breast cancer, we analyzed the relationship between TIPE1 expression and clinical pathology variables." (PMID 31179241, 2019). "In this study, we investigated that TIPE1 suppresses breast cancer cell proliferation in vitro and in a mouse xenograft model." (PMID 31179241, 2019). "Furthermore, TIPE1 expression in breast cancer tissues is downregulated compared to matched adjacent tissues, and its expression is positively correlated with patient lifespan." (PMID 31179241, 2019). "More importantly, TIPE1 expression is downregulated in breast cancer tissues and is positively correlated with patient lifespan, indicating that it might serve as a therapeutic target and a diagnostic biomarker for breast cancer." (PMID 31179241, 2019). "TIPE1 was downregulated in breast cancer compared to its paired control." (PMID 31179241, 2019). "To identify whether TIPE1 suppressed the proliferation of breast cancer cells specifically via the inhibition of ERK signaling, we further used the ERK shRNA and its pharmacological inhibitor and activator to perform next experiments." (PMID 31179241, 2019). "Then, we investigated whether breast cancer patients with lower TIPE1 levels had a poorer prognosis than patients with higher TIPE1 expression." (PMID 31179241, 2019). "In this study, we demonstrated that TIPE1 serves as a tumor suppressor gene in breast cancer." (PMID 31179241, 2019). "Furthermore, the expression of TIPE1 is decreased in breast cancer tissues compared to matched adjacent tissues, and its expression is positively correlated with patients' lifespan." (PMID 31179241, 2019).
breast carcinoma (continued). "Moreover, we compared the expression levels of TIPE1 in breast cancer specimens and their matched adjacent tissues." (PMID 31179241, 2019). "Subsequent results showed that TIPE1 contributes to an inhibitory effect on ERK phosphorylation, suggesting that TIPE1 might serve as an inhibitor of breast cancer proliferation." (PMID 31179241, 2019). "Here, we speculated how TIPE1 performs its biological functions in breast cancer." (PMID 31179241, 2019). "Therefore, we hypothesized that TIPE1 decreases breast cancer cell proliferation primarily through ERK signaling." (PMID 31179241, 2019). "The results showed that TIPE1 expression was decreased in breast cancer cell lines compared to non-cancer cell line." (PMID 31179241, 2019). "Thus far, the clinical significance and biological function of TIPE1 in breast cancer have not been demonstrated." (PMID 31179241, 2019). "The results showed that, consistent with our gene chip result, TIPE1 almost completely inhibited ERK phosphorylation (p-ERK) but not p-p65, p-mTOR, pS6, or p-MEK in breast cancer cells." (PMID 31179241, 2019). "The results showed that, consistent with our gene chip result, TIPE1 preferentially inhibited the ERK phosphorylation (p-ERK), but not p-p65, p-mTOR, p-S6, or p-MEK, in breast cancer cells." (PMID 31179241, 2019).
lung carcinoma (4 papers, 2017 to 2020). "In the present study, we attempted to investigate the expression and predicting role of TIPE1 by lung cancer tumor microarray and found lower TIPE1 expression in the lung tumor tissue, and TIPE1 expression positively correlated with tumor patient survival." (PMID 29108244, 2017). "Overexpression of TIPE1 by lentivirus system in TIPE1-downregulated lung cancer cells significantly diminished cell growth and colony formation, companied with proliferation inhibition, apoptosis induction and invasion inhibition." (PMID 29108244, 2017). "Consistently, using a homograft tumor model in Balb/c mice, we discovered that TIPE1 prevented the growth and tumor weight of murine lung cancer homografts." (PMID 29108244, 2017). "Collectively, we demonstrated the inhibition role of TIPE1 on lung cancer cell invasion and migration via regulating MMP expression." (PMID 29108244, 2017). "Collectively, TIPE1 inhibited lung cancer tumorigenesis via inhibiting proliferation and inducing apoptosis in vivo." (PMID 29108244, 2017). "Immunohistochemistry for TIPE1 expression in lung cancer tissues array indicated that TIPE1-positive cells were rarely observed among lung cancer cells." (PMID 29108244, 2017). "Various in vitro results demonstrated the inhibition role of TIPE1 on tumor growth and invasion in lung cancer cells." (PMID 29108244, 2017). "Furthermore, TIPE1 can serve as a potential molecular target in breast, gastric and lung cancer, as it is capable of modulating tumour growth and metastasis." (PMID 32588529, 2020). "Similarly, in a homograft tumor model in Balb/c mice, TIPE1 expression inhibited the tumor growth and reduced the tumor weight of murine lung cancer homografts, suggesting that TIPE1 acts as an anti-tumor molecule in lung cancer." (PMID 30586922, 2018). "Our findings revealed the anti-tumor role of TIPE1 in lung cancer cells and TIPE1 might be a novel prognostic indicator for lung cancer patients." (PMID 29108244, 2017). "Next, we investigated the mechanism of TIPE1 on lung cancer cell growth by flow cytometry." (PMID 29108244, 2017). "To determine the functional effects of TIPE1 on the biological behaviors of lung cancer cells, we first detected basal TIPE1 mRNA and protein expression in five colorectal cancer cell lines and normal lung epithelial cell MRC-5 by qPCR and western blotting analysis, respectively." (PMID 29108244, 2017). "But, the function and predicting role of TIPE1 in lung cancer is still confused." (PMID 29108244, 2017). "However, the expression and biologic functions of TIPE1 in lung cancer are largely unknown." (PMID 29108244, 2017). "To confirm TIPE1 expression in lung cancer tissues, we examined TIPE1 mRNA expression in ten paired nontumor and tumor tissue samples derived from lung cancer patient." (PMID 29108244, 2017).